ASPH (aspartate beta-hydroxylase)
Diseases named in the same sentence as ASPH in open-access papers (continued):
Sharing a sentence is not in itself a finding about the gene and the disease.
tumor (continued). "While ALDH18A1 was uniformly expressed across CCC and PCC tumors, ASPH expression was highly variable in both tumor types." (PMID 39858632, 2025). "Aspartate β-hydroxylase (ASPH) contributes to carcinogenesis by promoting tumor cell proliferation, migration, and invasion." (PMID 40655119, 2025). "ASPH expression in primary tumors is predictive of clinical outcomes, and its inhibition decreases tumor progression in a preclinical model." (PMID 40149287, 2025). "We have previously shown that ASPH is expressed in some carcinomas, and ASPH blockade in preclinical models of these malignancies inhibits tumor progression." (PMID 40149287, 2025). "In this study, we determined the impact of ASPH inhibition on both innate and adaptive anti-tumor immune responses and analyzed the phenotypic profiles of immune cells within the spleen and tumor microenvironment (TME)." (PMID 40655119, 2025). "To explore effects on both innate and adaptive immunity, we combined ASPH inhibition with either immunostimulatory CpG motif (ODN1826) treatment or DNA vaccination targeting the tumor-specific antigen HPV16 E7, respectively." (PMID 40655119, 2025). "CS’s abundant expression of aspartyl-asparaginyl-β-hydroxylase (ASPH), which drives invasive tumor growth via Notch and PI3K/mTOR activation, opens opportunities for treatment in combination with standard Doxorubicin (DOX) chemotherapy." (PMID 40427168, 2025). "The positive expressions of ASPH were significantly higher in the cases of poorly differentiation, large tumor size, high TNM stage, lymph node metastasis, invasion and no resection (only biopsy) of SC/ASC and AC." (PMID 40110547, 2025). "To investigate the function of ASPH in mouse tumor cell lines, we knocked out the ASPH gene in TC-1 cells by using the CRISPR/Cas9 system." (PMID 38356711, 2024). "Several animal tumor models have also demonstrated anti-tumor effects of selective inhibition of ASPH activity 8,10,14-17." (PMID 38817852, 2024). "The CIS representation on our tumor array is admittedly low, and this observation needs to be verified; however, overall, the upregulation of ASPH in the tumors is clearly demonstrated." (PMID 38732216, 2024). "We selected for our study MO-I-1151, a well-tested inhibitor of the β-hydroxylase activity of ASPH, with anti-tumor effects in other malignancies." (PMID 38732216, 2024). "GSK3β is widely recognized as a downstream target of AKT 20, and previous studies have shown that inhibition of ASPH enzymatic activity leads to increased GSK3β phosphorylation, which promotes tumor cell senescence 21,22." (PMID 38817852, 2024). "In this study, we attempted to find additional pathways affected by ASPH in mouse tumor cell lines using bulk RNA-seq." (PMID 38356711, 2024). "We found two members of the Ly6 family, Ly6a and Ly6c1, among the genes with differential expression induced by inhibition or deactivation of ASPH in tumor cells." (PMID 38356711, 2024). "We first performed an in vitro wound healing assay to assess the ability of our mouse tumor cells to migrate under the influence of the ASPH inhibitor." (PMID 38356711, 2024). "Analysis of cell cycle progression showed variable antiproliferative effects of ASPH inhibitors in different tumor cell lines." (PMID 38817852, 2024). "Inhibition of ASPH enzymatic activity resulted in significant effects on cell proliferation, migration, and invasion in the various tumor cell lines studied, which was consistent with the results of previous studies 14-16." (PMID 38817852, 2024). "To investigate the effect of ASPH inhibitors on cell signaling in human tumor cell lines by western blot, we first examined ASPH expression using two monoclonal antibodies." (PMID 38817852, 2024). "The study revealed the diverse and complex behavior of tumor cell lines in response to ASPH inhibition." (PMID 38817852, 2024). "We then tested the effect of ASPH inhibition on Ly6a and Ly6c production in four other mouse tumor cell lines." (PMID 38356711, 2024).
tumor (continued). "Both ASPH inhibitors were found to be potent suppressors of proliferation in all the tumor cell lines tested." (PMID 38817852, 2024). "The uniformly high expression of ASPH across all tumor stages prevented a meaningful analysis of the impact of ASPH on patient survival in our cohort of samples." (PMID 38732216, 2024). "Our study contributes to this understanding by examining the effect of ASPH inhibition on the Notch1 pathway in various tumor landscapes." (PMID 38817852, 2024). "To investigate the potential inhibitory effects of the ASPH inhibitors MO-I-1151 and MO-I-1182 on cell growth, we examined their effects on cell proliferation and clonogenic survival in a variety of human tumor cells." (PMID 38817852, 2024). "We showed the suppressive effect of ASPH inhibitors on cyclin D1 expression, c-myc phosphorylation, and the transition from G1 to S phase in the examined tumor cell lines." (PMID 38817852, 2024). "The high heterogeneity in the responses of individual tumor cell lines to ASPH inhibitors, both quantitatively and qualitatively, underscores the complex network of mechanisms that are regulated by ASPH and influence the efficacy of ASPH inhibition." (PMID 38817852, 2024). "To investigate the effect of ASPH inhibitors on the migratory ability of human tumor cell lines, we used a wound healing assay." (PMID 38817852, 2024). "Specific and selective small molecule inhibitors (SMIs) have been designed to target the hydroxylase activity of ASPH; these compounds inhibit tumor development and metastasis." (PMID 38732216, 2024). "These SMIs showed promising results in in vitro and in vivo experiments 5,8,25, with up to 80% reduction of ASPH enzymatic activity and a substantial decrease of proliferation, migration, and invasion of tumor cells in different cancer models 4,5." (PMID 38356711, 2024). "Reduced production of the Ly6D and Ly6K proteins was shown after ASPH inhibition in human tumor cell lines." (PMID 38356711, 2024). "Labyrinthin (LAB) is a distinct pan-adenocarcinoma tumor-specific target composed of 255 amino acid (AA) proteins within the 758 AA of the intracellular aspartyl/asparaginyl beta-hydroxylase (ASPH) that was discovered in 1985." (PMID 36765881, 2023). "The ASPH protein aggregates on the surface of tumor cells, and contributes to inducing tumor cell migration, infiltration, metastasis, and immune modulation." (PMID 36765881, 2023). "ASPH participants in regulating calcium homeostasis and the malignant transformation of tumor cells." (PMID 37004045, 2023). "Several previous studies suggested that ASPH is highly expressed in various tumor types including GC, and ASPH overexpression predicts a worse prognosis." (PMID 36982561, 2023). "ASPH is necessary and sufficient to promote tumor cell migration, invasion, motility, and distant metastatic spread both in-vitro and in-vivo." (PMID 37046994, 2023). "An increasing number of studies have been published and have shown that ASPH is related to the malignant transformation and invasiveness of tumor cells." (PMID 37004045, 2023). "We showed that ASPH knockout enhanced the inhibitory effects of chemotherapeutic drugs on the cell proliferation, migration, and invasion in vitro and suppressed tumor progression in vivo." (PMID 36982561, 2023). "In view of the proven important role of ASPH in promoting the aggressive and malignant behaviors of tumor cells, we assessed the effect of the knockout of ASPH on proliferation, migration and invasion in knockout cell lines." (PMID 36982561, 2023). "We are led to believe that combined therapy allows ASPH peptides to be recognized, taken up, processed and presented as well as cross-presented by DCs since this λ phage acts as an adjuvant to display tumor restricted molecules such as ASPH." (PMID 35392977, 2022). "We have recently identified anti-tumor effects of this λ phage vaccine that targets ASPH expressing HCC." (PMID 35392977, 2022).
tumor (continued). "Subsequently, ASPH interacts with immune system and serves as a tumor associated antigen (TAA) stably presented on a broad spectrum of tumor tissue types and represents an ideal target for immunotherapy." (PMID 35392977, 2022). "Endogenous expression of ASPH in BNL or 4 T1 induced tumor remains in the same range as in naturally developed human HCC or TNBC." (PMID 35392977, 2022). "We have demonstrated that a λ phage vaccine construct expressing a N-terminal peptide of ASPH when combined with a checkpoint inhibitor substantially reduces both primary tumor growth and multi-organ metastasis in murine models of TNBC and HCC." (PMID 35392977, 2022). "Using HCC and TNBC murine models, a λ phage vaccine construct which displays the N-terminal ASPH peptide modestly inhibits subcutaneous tumor growth and progression." (PMID 35392977, 2022). "ASPH is found to guide tumour cells to secrete EVs carrying pro‐invasive/pro‐metastatic components such as active Notch receptor and ligand, and regulators ADAMs and downstream MMPs." (PMID 33586248, 2021). "ASPH is also thought to lead to immune surveillance escape and promotes tumor growth by direct effects on NK-cells, including reducing NK-cell viability and cytotoxicity." (PMID 35004304, 2021). "Dendritic cell vaccination studies in a rodent model of biliary cancer showed successful passive vaccination with naïve dendritic cells that were matured in vivo in the presence of ASPH, leading to tumor regression, along with ASPH-specific T-cell responses." (PMID 35004304, 2021). "Digital pathology analysis showed that ASPH exerted its pathological activity in the invasive margin of the tumor, affecting invasive front morphology, tumor budding and patients’ overall survival." (PMID 32295249, 2020). "AspH is upregulated on the surface of malign cancer cells; increased AspH levels correlate with tumour invasiveness." (PMID 32457455, 2020). "The exact mechanism of how AspH promotes tumour invasiveness is poorly understood, though there is some evidence it is mediated by the notch receptor and its ligands, which contain multiple EGFDs bearing the consensus sequence for AspH-catalysed hydroxylation." (PMID 32457455, 2020). "As phosphorylation of pRb inactivates its tumor-suppressor function, ASPH can contribute to the progression of cell cycle via interaction with pRb." (PMID 32811566, 2020). "ASPH is a highly tumor specific antigen that is differentially overexpressed in multiple human cancers but not in healthy adult tissue and is associated with tumor cell growth, motility and invasiveness." (PMID 32046729, 2020). "In summary, ASPH is a promising target for anti-tumor and anti-metastatic therapy based on inactivation of catalytic activity and/or immunotherapy." (PMID 32811566, 2020). "ASPH belongs among the most important biological targets to control migration and invasion of tumor cells, as its overexpression has been observed in 70–90% of human solid tumors." (PMID 32811566, 2020). "Two main pathways, Notch and SRC, through which ASPH promotes the tumor growth have been identified." (PMID 32811566, 2020). "ASPH plays important roles in tumor progression through the activation of the Notch signaling pathway, disruption of mitochondrial functions and inhibition of the antitumor activity of natural killer lymphocytes." (PMID 32295249, 2020). "Aspartate-β-hydroxylase (ASPH), a transmembrane protein that catalyzes Notch receptors and ligand activation, is involved in tumor invasion." (PMID 32295249, 2020). "Humbug has a potential role in cell adhesion and calcium flux and similar to ASPH, its overexpression has been correlated with aggressive tumor-cell behavior." (PMID 32811566, 2020). "Notch and SRC signaling are probably major pathways influenced by ASPH and contributing to increased aggressiveness of tumor cells that was verified in in vivo models." (PMID 32811566, 2020).
tumor (continued). "Specific third-generation small molecule inhibitor targeting ASPH enzymatic activity substantially disrupted primary tumor growth and impeded pulmonary metastasis." (PMID 31888763, 2019). "ASPH fosters primary tumor development and pulmonary metastasis in PDX models of PDAC, which is blocked by a leading compound specifically against ASPH enzymatic activity." (PMID 31888763, 2019). "Compared to Vector, exogenous ASPH generated more aggressive tumors as elicited by both increased weight of primary tumor and widespread metastases to the lungs, lymph nodes, spleen, intestine (colon), mesentery, or liver in orthotopic murine models." (PMID 31694640, 2019). "ASPH expression profiling in the original tumor derived from PDAC patients was continuously recapitulated following serial passages for over 56 weeks." (PMID 31888763, 2019). "AspH localises to the endoplasmic reticulum (ER) in normal cells, but (at least part of AspH) localises to the surface of tumour cells and its hydroxylase activity was reported to enhance cell migration." (PMID 31659163, 2019). "Our previous study demonstrated an increased expression of aspartate β-hydroxylase (ASPH) in HCC tissues, which was associated with tumor invasiveness and a worse prognosis." (PMID 28714949, 2017). "The IHC staining results revealed that activated Notch1 signaling was very robust in sh-Luc treated tumor tissue as compared to sh-ASPH treated cells, suggesting that targeting ASPH with shRNAs substantially inhibits Notch signaling and blunts CCA growth." (PMID 26954680, 2016). "Intrahepatic inoculated BDE-Neu cells transfected with sh-Luc served as a control and demonstrated growth of large tumors around the bile ducts, but BDE-Neu cells with stably transfected sh-ASPH had a substantial reduction in tumor growth." (PMID 26954680, 2016). "Lentiviral induced ASPH overexpression in MIA PaCa2 PC cells with low endogenous expression levels was notable for translocation of the protein to the tumor cell surface." (PMID 25483102, 2015). "We are currently obtaining similar information on PC patients to determine the relationship between ASPH expression in tumor tissue and clinical outcome." (PMID 25483102, 2015). "Studies were performed to determine if ASPH overexpression can promote tumor growth in Balb/c nude mice inoculated subcutaneously (s.c.)with MIA PaCa2 cells." (PMID 25483102, 2015). "Furthermore, ASPH contributes to heightened tumor drug metabolism, hence raising the IC50 values for gemcitabine and paclitaxel." (PMID 40110547, 2025). "Major limitations of this study include its focus on T cells and limited assessment of other subpopulations of immune cells, as well as analysis of ASPH inhibition combined with DNA vaccination in only one tumor model, which restricts the generalizability of the results." (PMID 40655119, 2025). "Given the growing importance of immunotherapy in cancer treatment, we investigated how ASPH inhibition might influence the anti-tumor immune response in vivo." (PMID 40655119, 2025). "ASPH, a type II transmembrane protein of the α-ketoglutarate-dependent dioxygenase family, has functional roles in cell motility utilized for infiltrative and metastatic tumor growth." (PMID 40427168, 2025). "Furthermore, ASPH inhibits GSK3β phosphorylation, interfering with upstream kinase communication, delaying cellular senescence, and promoting tumor progression." (PMID 41312363, 2025). "However, combining ASPH inhibition with the PADRE.E7GGG DNA vaccine significantly inhibited tumor growth." (PMID 40655119, 2025). "The abolishment of ASPH’s catalytic activity by either site-directed mutagenesis of its critical His-675 residue or deletion of the molecule’s C-terminus prevents Notch activation and reduces cell motility and tumor growth." (PMID 40427168, 2025). "ASPH KO decreases cell viability, reinforcing its importance in this tumor." (PMID 40149287, 2025).
tumor (continued). "Therefore, this study aimed to investigate the effect of ASPH inhibition on the induction of anti-tumor immunity and to analyze the immune cells involved." (PMID 40655119, 2025). "ASPH has been found to be overexpressed in various malignant tumors, and The hydroxylase activity it possesses holds a crucial function in fostering malignant tumor characteristics, encompassing tumor growth, proliferation, invasion, and metastasis." (PMID 39980566, 2025). "ASPH plays a recognized role in tumor initiation and progression in several types of cancer." (PMID 40655119, 2025). "The results indicate that high expression of ASPH results in drug tolerance in tumor patients." (PMID 40110547, 2025). "Understanding the precise mechanisms by which ASPH inhibitors modulate cell signaling in tumor cells may pave the way for improved cancer treatment." (PMID 38817852, 2024). "However, the expression of ASPH in the primary tumors of HNSCC increases with the grade of the tumor." (PMID 38732216, 2024). "In general, ASPH could facilitate tumor growth mainly through the activation of the Notch signaling pathway, so it’s possible to block the self-renewal and proliferation of CSC and tumor progression by targeting the Notch signaling pathway." (PMID 38702698, 2024). "We used the model to establish the ability of the ASPH inhibitor MO-I-1151 to inhibit the invasion of HNSCC tumor cells into Matrigel, and we showed an additive inhibitory effect of its combination with a recently described heparan 6-O-endosulfatase (SULF2) inhibitor, HfFucCS." (PMID 38732216, 2024). "The demonstration that ASPH enzymatic activity promotes tumor growth and metastasis raised the possibility that inhibition or reduction of this activity may be used in cancer therapy." (PMID 38356711, 2024). "When upregulated in tumor cells, ASPH was found on the cell surface where its catalytic site located in the C-terminal region is exposed to the extracellular environment and can be recognized and attacked by the host antibody response and monoclonal antibodies 12-14." (PMID 38356711, 2024). "In addition, the presence of circulating tumor cells (CTCs), circulating tumor DNA (ctDNA), and changes in the abundance of some proteins (CXCL10, ASPH, SPP2, ENO2, etc) all predicted the risk of postoperative recurrence 8-12." (PMID 39430252, 2024). "Among the identified genes that are differentially expressed after inhibition of ASPH, there are other genes that may be involved in carcinogenesis and/or contribute to tumor development." (PMID 38356711, 2024). "We tested the ability of the MO-I-1151 ASPH inhibitor alone or in combination with a recently described SULF2 inhibitor HfFucCS with regard to the invasion of HNSCC tumor cells in a spheroid co-culture model with a primary HNSCC cancer-associated fibroblast (CAF 61137)." (PMID 38732216, 2024). "Although ASPH downregulation plays a tumor-suppressive role in GC chemotherapeutic agents could further potentiate these anti-tumor functions." (PMID 36982561, 2023). "ASPH has a higher level of expression in tumor tissues compared with normal tissues in GC." (PMID 36982561, 2023). "Aspartate β-hydroxylase (ASPH) represents an attractive target which is a highly conserved transmembrane enzyme overexpressed in human GC, and participates in the malignant transformation by promoting tumor cell motility." (PMID 36982561, 2023). "Therefore, ASPH is one of the most important biological targets to control tumor cells’ migration and invasion." (PMID 37004045, 2023). "In GC, we also observed that ASPH promoted tumor cell migration via regulating the EMT process." (PMID 36982561, 2023). "Moreover, small molecular inhibitors (SMIs) of ASPH have been extensively developed and the anti-tumor effect was verified by several cancer models." (PMID 36982561, 2023). "ASPH promotes tumor cell proliferation, migration, invasion and metastasis." (PMID 35392977, 2022).